CD4 (CD4 molecule)
Diseases named in the same sentence as CD4 in open-access papers (continued):
Sharing a sentence is not in itself a finding about the gene and the disease.
infection (continued). "A flow cytometry-based assay capable of measuring SIV transcription in CD4 T cells undergoing infection was utilized." (PMID 36000842, 2022). "We estimated rates of reactivation and reconstitution, and identified distinct phases in which dynamics were either dominated by new infection of CD4 T cells, or by reactivation of the latent reservoir." (PMID 35969641, 2022). "Fucose levels, however, are higher in PBMCs than endometrium, suggesting that the fact that AOLHigh endometrial CD4+ Tm cells aren’t preferentially targeted for infection cannot be explained by exceptionally high levels of fucose expression." (PMID 35787792, 2022). "In this animal, gut CD4+ T cells decreased from 50% to 18% of T cells at week 2 but then increased to pre-infection levels as the viremia declined." (PMID 35714165, 2022). "Surprisingly, IFN-γ producing CD4 T cells from the FRT expressed low levels of T-bet throughout infection, suggesting that classical T-bet-expressing Th1 cells are inefficiently generated and therefore unlikely to participate in bacteria clearance." (PMID 35196366, 2022). "Both viruses initially infect DCs and propagate the infection to CD4+ T cells through cell-to-cell transmission using mechanisms including the formation of virologic synapses, viral biofilms, and conduits." (PMID 36146843, 2022). "In particular, both CD4+ and CD8+ T cells are highly associated with protection against early infection of Salmonella." (PMID 35898510, 2022). "We mapped 955 single peptide‐specific CD4+ T‐cell responses in a cohort of COVID‐19 patients (n = 8), uninfected vaccinees (n = 16) and individuals who experienced both infection and vaccination (n = 11)." (PMID 35957961, 2022). "HICs generally maintain CD4+ T cell counts over 500 cells/mm3, however those that overflow this threshold show a progressive decrease in CD4 numbers, perhaps as a consequence of immunological activation and early cellular senescence derived from infection." (PMID 35844607, 2022). "Consistently, we observed that the frequency of AIM+ CD4+ T (SARS-CoV-2-specific CD4+ T) cells in the infection-only group was much lower than that in the hybrid-immunity group." (PMID 36494338, 2022). "In contrast to myeloid cells, DCs, and ECs, we only detected few transcripts that are significantly elevated with infection in T cells including B2m, Satb1, Gm42418, Gimap6 in CD4+ T cells and Gm42418 in CD8+ T cells." (PMID 35789215, 2022). "It is possible that after infection, CD4+ T cells migrate from peripheral blood to the spleen, a major organ during infection with blood pathogens, such as Babesia." (PMID 36466866, 2022). "IFN‐γ can be secreted by CD8+ T cells and NK cells, and IL-2 production by HBV-specific CD4+ T cells plays an important role in the efficient development of cytotoxic effector CD8+ T cells that contribute to the elimination of infection." (PMID 36389814, 2022). "Because we and others have previously shown that romidepsin and bryostatin‐1 decrease de novo infection in macrophages and CD4+ T cells, we studied the impact of LRAs on their polarization status." (PMID 36480653, 2022). "In this infection model, the protective effect of the CD4+ T cells on the 3D-tissue model was blocked after pre-incubation of the immune-cells with T6030504, resulting in increased invasion of C. albicans into the model." (PMID 35208698, 2022). "We also examined the effect of pre-infection plasma cytokine levels on CD4+ T cell decline below 500 μl prior to ART initiation." (PMID 35165387, 2022). "CD4+ T cells are the main regulators of the immune response by secreting a variety of cytokines, recruiting immune cells to the site of infection, and initiating the differentiation of CD4+ T cell subsets with different effector functions." (PMID 35547626, 2022). "We therefore analyzed the CD4+/CD8+ memory T cell response among the infection status groups and found that the trends mimic those of the canonical CD4+ or CD8+ memory T cell response." (PMID 35422803, 2022).
infection (continued). "In patients with severe infection, CD4+ T lymphocytes with a pro-inflammatory profile and producers of IL-2 and IFN-γ are found while CD4+ CD25high producers of IL-10 are almost absent." (PMID 35203344, 2022). "TfhD3 generated under HIVYu2b infection showed an intermediate transcriptomic profile between ex vivo CD4+ T cell subsets and TfhD3 uninfected controls." (PMID 34984326, 2022). "During pathogen infection in the lung, pathogen-specific CD4+ and CD8+ cells are primed in the lung-draining lymph nodes by antigen-presenting DCs that migrate from the infected area in the lung." (PMID 35615351, 2022). "Early and persistent immunologic abnormalities that occur after experimental and natural infection include decreases in both the number and relative proportions of CD4+ T cells in the peripheral blood as well as in lymphoid tissues." (PMID 35632665, 2022). "In SARS-CoV-infected patients, the acute phase of infection was correlated with a severe reduction in the number of T cells in the blood, with a sharp reduction in the number of CD4 and CD8 T cells compared with that in healthy controls." (PMID 35017320, 2022). "The BCG-DNA-boosted mice sustained the largest proportion of multifunctional CD4+ T cells during infection." (PMID 36267175, 2022). "When the CD4-PP was added 2 h after initiation of the infection, the peptide was unable to reduce the survival of the P. aeruginosa-type strain." (PMID 35821354, 2022). "At 1-year after infection, more than 90% of the convalescents generated memory CD4 or CD8 T memory responses, preferably against the SARS-CoV-2 M peptide pool." (PMID 35240947, 2022). "Following a single infection cycle in activated CD4+ T cells isolated from healthy donors (n = 6), we found that the TCF-4 binding site mutant virus showed a 2.3-fold increase in HIV transcripts compared to wildtype HIV-REJO (p = 0.016)." (PMID 35255110, 2022). "This condition usually develops after blood CD4+ cells fall below 200/μl and represents an extension of infection from meninges into the brain parenchyma." (PMID 35775044, 2022). "SIV-specific CD4+ T cells were shown to be proliferating memory cells that were primed by vaccination and rapidly mobilized upon infection." (PMID 36033843, 2022). "These cells rapidly expanded upon infection and effectively restricted virus replication as determined by CD4 T cell depletion studies." (PMID 35260804, 2022). "In these infection models, bacterial clearance coincided with the reactivation of Th17 polarised CD4+ Trm which accelerated neutrophil recruitment into the airways." (PMID 35637249, 2022). "The results highlighted the potential role of CD4 CTL and CD4/CD8α DN cells in protection against transplacental infection." (PMID 36798517, 2022). "Activated CD4+ effector T cells were fewer in 14‐day old pups, and less terminally differentiated than adult effector T cells on day 8 and 14 of infection." (PMID 36131528, 2022). "CD4 T cells elicited by infection also promote the recruitment of innate effectors to the lung, blunting virus replication, and they can also provide protection by their cytotoxic activity that has the potential to directly eliminate infected cells." (PMID 35215193, 2022). "Both HIV-1 and HIV-2 diversity has been reported to increase over the course of infection, and the diversity rate to be positively correlated with the rates of CD4+ T-cell decline." (PMID 36366545, 2022). "We then challenged these mice by a sublethal dose of X47 virus to decipher which functional memory CD4 T cell subsets that expanded in the lung and in the mediastinal lymph nodes (mLN) in response to infection." (PMID 35260804, 2022). "NP contains many epitopes targeted by T cells, and targeting these epitopes can be highly protective in the mouse model and both CD8+ and CD4+ T cell responses correlate with reduced infection in humans." (PMID 35945226, 2022).
infection (continued). "In a humanized mouse model, we found that infection with wild type HTLV-1 virus resulted in polyclonal expansion of CD4+CD25+ T-cells." (PMID 36298639, 2022). "After the elimination of DENV infected target cells, memory CTL CD4 cells express DENV specific HLA class II proteins for protection against secondary infection leading to severe DENV disease." (PMID 36159640, 2022). "Dendritic cells (DCs) promote HIV-1 transmission by acting as Trojan horses, capturing viral particles, facilitating the infection of CD4+ T-cells." (PMID 35802715, 2022). "Then, MDV infection enters the latency phase at around 7–10 dpi; the main target cells in this infection phase are CD4+ T cells." (PMID 36680047, 2022). "This, in addition to the subsequent activation of CD8 and CD4 T cells, characterizes part of the immune response taking place in order to control infection or eventually form granulomas." (PMID 36266777, 2022). "We found that NK cells contribute to host CD4 Th1 T cell responses early following infection and dietary antigen-specific CD4 Th1 and Treg responses." (PMID 35993365, 2022). "Work done by our group demonstrated that, in mice, some of the age-related deficits in CD4 T cell function during infection are cell extrinsic and thus regulated by the aged microenvironment." (PMID 36119079, 2022). "Cis-infection (also called second-phase transfer) occurs when a CD4 T cell interacts with MNPs 72 h or longer after the MNP has been infected via the CD4/CCR5 pathway, with the MNP actively producing virus that buds from the plasma membrane." (PMID 35173293, 2022). "Infection induced significant changes in the percentage of CD4+CD8α+ T cell subpopulations in the blood of turkeys (P = 0.021)." (PMID 35883183, 2022). "HIV is responsible for significantly depleting CD4 T cells and therefore reducing the population of infection-specific effector cells." (PMID 36354898, 2022). "Upon challenge infection, there was a marked increase in CD4+ T cell population from the vaccinated mice (** p < 0.01)." (PMID 36140395, 2022). "The frequency of ESAT61-20-tetramer binding CD4 T cells in the lungs of Vhl cKO after infection with M. tuberculosis was reduced when compared to that of WT mice." (PMID 36064840, 2022). "We noticed a significantly lower population of IFN-γ expressing CD4+ cells in IL-10+ Breg recipient mice in comparison to the control group of animals 9 days post infection." (PMID 35625397, 2022). "Merging our single-cell clonal and transcriptomic datasets together allowed us to track the lineage commitment of CD4+ T cell clones from the GP66-specific repertoire during chronic LCMV Cl13 infection." (PMID 36255051, 2022). "In naïve mice, CD4+CD69+CD11a+ T cells were scarce but from 3 dpi the frequency was significantly increased with a peak in numbers by day 8 post infection." (PMID 36275685, 2022). "PMNs differentially modulated the capacity of T-cell proliferation in early infection by increasing CD4+ T-cell proliferation while decreasing it in CD8+ T cells." (PMID 35185880, 2022). "Th cells, which are CD4+ T cells, play an important role in protecting the body from infection and secrete both proinflammatory cytokines (e.g., IFN-γ, TNF-α, and IL-6) and anti-inflammatory cytokines (e.g., IL-10)." (PMID 35001010, 2022). "In terms of functionality, these changes are accompanied by attenuation of the unstable Th1/Th17-like Treg phenotype and proinflammatory polarization of CD4+ (which was still observed at 3 months after primary infection)." (PMID 35757700, 2022). "There are many studies that state CD4-mediated cellular immunity is required to prevent infection from Candida." (PMID 36000133, 2022). "This route of transmission has been widely examined, and this population is often tested for HIV; therefore, they enter care at an early stage of infection, and they also have higher baseline CD4+ cell counts." (PMID 35407496, 2022).
infection (continued). "Our framework extends previous models of rebound in adults by incorporating mechanisms of the natural decline and infection-induced reconstitution of CD4 T cells in young infants." (PMID 35969641, 2022). "For additional validation, we re-analyzed LCMV-specific CD4+ T cells isolated 10 days post-infection with LCMV Armstrong." (PMID 35829695, 2022). "Typically, the infection occurs on the decline of CD4 + T cell count (below 50 cells/μL) among HIV-infected patients." (PMID 35130846, 2022). "They do this by trafficking to T cell zones during infection, where they prime CD4+ and CD8+ T cells and promote cytotoxic T cell activity." (PMID 35880171, 2022). "HIV enters human embryonic microglia through a receptor on CD4+ T lymphocytes, and the infection can further spread in the CNS via the contact of glial cells with infected CD4+ T lymphocytes." (PMID 35891500, 2022). "It is noteworthy that in the basal condition (not stimulated), higher production of granzyme, IFN-γ, and CD107a was observed in CD4+ T lymphocytes of patients with severe infection compared to uninfected individuals." (PMID 36359755, 2022). "Three tissues sampled post-infection (lung, mediastinal lymph node (mLN), and spleen) were used to assess CD4 T cell reactivity, which include both the site of infection and peripheral lymphoid tissue." (PMID 35215193, 2022). "CD4+ T cell responses against SARS-CoV-2 were more prominent than the CD8+ T cell response in adults with mild-to-moderate infection, while qualitatively impaired CD4+ T cell responses have been reported for critically ill patients." (PMID 35197982, 2022). "In contrast, expansion of systemic bulk CD4+ T cells following either infection was considerably more modest, possibly reflecting the early time point studied." (PMID 35983063, 2022). "Taken together, these results strongly suggest a primary role for CD4 T cell–dependent mechanisms, including antibodies in vaccine immunity to infection with the homologous USA-WA1/2020 strain of SARS-CoV-2 virus in mice." (PMID 35561224, 2022). "coli was significantly lower than that in group NOB-uninfected at 12 h post-infection (p < 0.01), the percentage of CD4+T cells in group NOB-E." (PMID 35720836, 2022). "The influenza B-virus specific CD4 T cells partition into the lung, with the majority of cells at day 10 post infection residing in the lung tissue." (PMID 35215193, 2022). "The latent reservoir is thought to be seeded within days of infection via direct infection of CD4+ T cells in a resting state, or from infection of activated CD4+ T cells which later transition to a quiescent state." (PMID 35255110, 2022). "The antiviral effect of EA in the gel formulation (Ellagel), as would be used for vaginal application, was investigated by the inhibition of infection of UC87.CD4.CCR5 cells with R5-tropic pBaLEnv-recombinant HIV-1." (PMID 36432041, 2022). "Overall, these analyses revealed a profound and fast-adapting phenotypic heterogeneity of CD4+ T cell populations in response to different infection settings." (PMID 35829695, 2022). "Triggering the fibroblasts antimicrobial response via expression of antimicrobial peptides such as β-defensins and LL-37 required the presence of PBMCs or CD4+ T cells in the infection model." (PMID 35208698, 2022). "This short-lived process cannot be captured by the constant CD4 recruitment term exploited in many models of adult infection." (PMID 35969641, 2022). "We then evaluated the phenotypic alterations imposed by the in vivo infection over CD4+ and CD8+ intrahepatic T lymphocytes." (PMID 35720410, 2022). "Treatment of uroepithelial cells with CD4-PP altered the expression of CXCL8, encoding for the pro-inflammatory neutrophil recruiter IL-8, during in vitro infection." (PMID 35821354, 2022). "Our findings obtained following natural infection and in the context of mRNA vaccination suggest that the global CD4+ T cell response is retained also against Omicron." (PMID 35154116, 2022).
infection (continued). "As the initial site of infection, human CD4+ T cells in the vaginal mucosa were likely targeted and depleted in the early stages of HIV infection." (PMID 36146734, 2022). "Infection with Pb K173 resulted in a build-up of IL-10-producing leucocytes, mostly CD4+ and CD8+ αβ T cells, when compared to NI mice." (PMID 35768411, 2022). "As described in detail above, although DC-like MNPs are more efficient at HIV uptake, infection, and transfer of the virus to CD4 T cells, macrophages can also perform these functions." (PMID 35173293, 2022). "The CD11b+ DC subset isolated from the mLN on days 3–4 post JKD6159-gD infection activated gDT-2 CD4+ T cells directly ex vivo." (PMID 35637249, 2022). "Previous studies on immunity to infection with SARS-CoV-2 have shown that CD4+ T cell responses are mainly polarized to the Th1 type." (PMID 35924252, 2022). "It is remarkable that the CD4 T cells which are specific for diverse antigens of a pathogen, under particular circumstances of infection, often belong to the same subset." (PMID 35326834, 2022). "Upon infection, mice in the control cohort, displayed a significant decline in CD4+ T cell percentages and by Day 14, lost >97% of these cells in all mice in this group." (PMID 35079625, 2022). "In 2020, a study concluded that infection elicits a stronger (polyfunctional) CD4+ response compared to vaccination in organ transplant recipients and thereby likely offers a better protection against reinfection." (PMID 36052083, 2022). "Univariate analysis revealed a significant association between patient age, duration of HIV infection, clinical stage of infection, and CD4 T cell count with LEA." (PMID 35701157, 2022). "Consistent with these annotations, Th1 memory, Tfh memory and Central Memory (Tcm) populations were predominantly derived from virus-specific CD4+ T cells isolated at late timepoints after acute infection (see next section)." (PMID 35829695, 2022). "The vaccine initially showed promising results in preclinical evaluations in NHP models in terms of attenuating the infection in the acute phase, the maintenance and recovery of CD4+ T cells, and the control of viremia during the chronic phase of infection." (PMID 36033843, 2022). "Microglia are the resident form of myeloid cell in the CNS and, similar to macrophages, are known to express a low density of CD4 on the cell surface, making them a potential target of infection within the CNS." (PMID 35975998, 2022). "HIV enters the central nervous system (CNS) early during infection mainly through infected monocytes or CD4+ T lymphocytes and, to a lesser extent, as viral particles crossing the blood–brain barrier (BBB)." (PMID 35458559, 2022). "A study by Denhey at al. showed that vaccination and infection induced comparable levels of specific SARS-CoV-2 CD4+ T cells after three months in addition to comparable proportions of specific central CD4+ memory T cells." (PMID 35214700, 2022). "CD4 T cells are involved as early as 12-48 hours post infection in the immune response to recurrent human HSV infection and are also the most prominent effector cell by 4 days post onset of primary human lesions." (PMID 36211447, 2022). "Accordingly, after CD4+ T-cell depletion in vivo, the infection is sustained by long-living infected macrophages, marking them as an important component in HIV-1 reservoirs." (PMID 35893688, 2022). "Regarding the cellular response, a significant percentage of the circulating SARS-CoV-2-specific CD4+ T cells detected after two doses of CoronaVac exhibited a Tfh phenotype, similar to those observed following mRNA vaccination and infection." (PMID 36341425, 2022). "Even different epitopes derived from the same virus but implicated in different phases of infection, in this case CMV, induced differential expression of T-bet and Eomes in CMV-specific CD4+ T cells." (PMID 35903098, 2022).